CTLA4 (cytotoxic T-lymphocyte associated protein 4)
Diseases named in the same sentence as CTLA4 in open-access papers (continued):
Sharing a sentence is not in itself a finding about the gene and the disease.
tumor (continued). "In liver hepatocellular carcinoma (LIHC), the positive correlation between LRFN4 and immunotherapy targets such as PDCD1 and CTLA4 implies that LRFN4 can impact the interaction between immune cells and tumor cells, potentially modulating the efficacy of immune checkpoint blockade (ICB) therapy." (PMID 40386777, 2025). "While CTLA-4 is responsible for inhibiting the activation of naïve T-cells in the lymph node during the initial immune response, PD-1/PD-L1 and LAG-3 play significant roles in the tumor microenvironment." (PMID 40108693, 2025). "CTLA-4 IHC staining provides critical insights into HCC immunobiology, prognostic stratification, and therapeutic targeting, but varies by cellular compartment (TILs vs. tumor cells), which complicates prognostic interpretation." (PMID 40941632, 2025). "Furthermore, T cells within the TME undergo exhaustion, characterized by upregulation of immune checkpoint molecules such as PD-1, TIM-3, CTLA-4, and LAG-3, impairing anti-tumor functions." (PMID 40095115, 2025). "Even the increased CTLA-4 expression by Treg cells was not sufficient to suppress the anti-tumor response in Atg5ΔOX40 mice injected with B16 tumor cells." (PMID 40977681, 2025). "The immunologically “cold” tumor microenvironment (TME) characteristic of SCLC, marked by low immune infiltration, may render CTLA-4 inhibition insufficient to activate an adequate anti-tumor immune response." (PMID 40783512, 2025). "While CTLA-4 inhibitors such as ipilimumab have shown limited efficacy as monotherapy in HNSCC, combination strategies with PD-1/PD-L1 inhibitors are under exploration to enhance T-cell activation both at the tumor site and in draining lymph nodes." (PMID 41179287, 2025). "PD-1/PD-L1 interactions play a role in immune evasion by suppressing T cell activity within the tumor microenvironment (TME), while the binding of CTLA-4 on T cells leads to downregulation of the immune response, making these pathways potential immunotherapeutic targets in NMIBC." (PMID 40227644, 2025). "In addition, this molecule showed a positive correlation with the expression of PD-1, CTLA-4, TIGIT, LAG-3, and TIM-3, indicating its involvement in the immune exhaustion process in the tumor microenvironment." (PMID 40965626, 2025). "CTLA-4 and PD1/PD-L1 are crucial immune checkpoints facilitating tumor immune escape." (PMID 41378287, 2025). "However, the interaction between tumor cells and immune cells within the inflammatory microenvironment, along with various immune checkpoints such as IDO, IL-10, TGF-β, PD-1, and CTLA-4, results in T cell dysfunction." (PMID 40688079, 2025). "However, in the same context, MAIT cells exhibit increased expression of inhibitory receptors, including PD-1, CTLA-4, and TIM-3, which drive T cell exhaustion and impair their anti-tumor function." (PMID 40025566, 2025). "Another tetravalent symmetric antibody, 2MW4691, targets CCR8, a tumor-resident Treg-specific marker, with low CTLA-4 affinity, eliminating intratumoral Tregs via ADCC without compromising CD8+ T cell activation." (PMID 41394821, 2025). "Furthermore, our scRNA-seq analysis revealed that immune infiltrating subtype tumours had a high percentage of infiltrating GZMK CD8 T cells which exhibited very low levels of PD-1, CTLA-4, and other immune checkpoint genes." (PMID 39548315, 2025). "One study isolated exosomes from bone marrow MSCs, loaded them with siRNA targeting KRASG12D, and analyzed their effects on tumor cell KRAS signaling, FAS epigenetic regulation, and the immune microenvironment, validating their synergistic effect with anti-CTLA-4 therapy." (PMID 41024179, 2025). "Cisplatin normalized the tumor blood vessels, leading to increased infiltration of CD8+ T cells and upregulation of T cell activation markers IFN-γ and CXCR3, when combined with dual CTLA-4 and PD-1 blockade." (PMID 39757995, 2025). "In contrast, anti-CTLA-4 antibody treatment induced marked tumor regression irrespective of ULBP2 expression." (PMID 40558520, 2025).
tumor (continued). "Tumor cells inhibit the activity and function of immune cells through various mechanisms, including the secretion of immunosuppressive factors (TGF‐β, IL‐10, etc.)and the up‐regulation of the expression of immune checkpoint molecules (PD‐1, CTLA‐4, etc.)." (PMID 40135802, 2025). "In order to discern CTLA4 cytosolic or membrane localization, along with its ratio to CD28, we quantified and compared protein levels of CTLA4, CD28, and the ligand CD80 in the lymph nodes and in the TIME between the same patients representing specific tumor clusters." (PMID 40492347, 2025). "Currently, available CTLA-4-targeted ICIs, such as the humanized monoclonal antibody ipilimumab, block the CTLA-4-B7 pathway, enhancing effector T-cell proliferation and activation, thereby augmenting antitumor immune responses and tumor cell destruction." (PMID 40176803, 2025). "In addition, maturation of tumor surface antigens is affected by Treg expression of cytotoxic T cell antigen 4 (CTLA-4), and immune evasion of tumor cells results from the inability of anti-CTLA-induced immature T cells to recognize tumor surface antigens." (PMID 40420174, 2025). "After confirmation of tumor growth, cancer-bearing and non-cancer mice received combinatorial treatment of anti-CTLA-4 (1 mg per dose, twice per week) and anti-PD-1 (200 μg per dose, thrice per week) for three weeks." (PMID 40605058, 2025). "In a landmark mouse model study, CD40 agonist therapy alone induced substantial tumor shrinkage without requiring PD-1 or CTLA-4 checkpoint inhibition, highlighting a potent innate immune mechanism." (PMID 40821795, 2025). "Additionally, several preclinical studies in mouse models demonstrated that Fc-dependent depletion of tumor-infiltrating FOXP3+ regulatory T cells (Tregs), which highly express CTLA-4, co-defines the efficacy of anti-CTLA-4 therapy." (PMID 40460830, 2025). "In vivo, localized MWA selectively suppressed tumor growth without systemic toxicity, coinciding with a reduction in CTLA-4+ Treg subsets and an increase in TNFRSF4+ Tregs." (PMID 41208977, 2025). "Another promising combination is using both anti-PD-1 and anti-CTLA-4 antibodies, which together enhance the immune response by reducing the number of immunosuppressive cells (MDSCs) in the TME, helping the immune system to target the tumor more effectively." (PMID 40223032, 2025). "Interestingly, CTLA-4 blockade loses efficacy in CD4+ T cell-depleted mice, suggesting its anti-tumor effects rely on CD4+ T cell-mediated modulation of dendritic cells and microglia, offering new insights into its role in GBM treatment." (PMID 39911397, 2025). "Furthermore, immune checkpoint analysis revealed that ALDOA-high tumors exhibit reduced expression of key immune checkpoints, including PDCD1, CTLA4, and TIGIT, potentially reducing immune cell engagement with the tumor and further promoting immune evasion." (PMID 41239433, 2025). "Moreover, the intra-tumoral injection of SS1P was shown to enhance the efficacy of an anti-CTLA-4 ICI, administered i.p., in tumor-bearing mice." (PMID 40918456, 2025). "As early as 2005, in multiple mouse tumor models, researchers discovered that simultaneously blocking the independent redundant pathways mediated by anti-CTLA-4 and anti-PD1 could induce and/or expand the repertoire of tumor-reactive T cell epitopes." (PMID 40517166, 2025). "However, in the weakly acidic and glutathione-rich tumor microenvironment, ZIF-8 rapidly degrades, releasing KN046 to simultaneously block PD-L1 and CTLA-4 signaling pathways." (PMID 40474230, 2025). "Unfortunately, in the TME, these checkpoints, such as CTLA-4, programmed death receptor–1 (PD-1), Nectin-4, and lymphocyte activation gene 3 (LAG3) on T cells, are engaged with their partner ligand on tumor cells to downregulate immune response, leading to reduced cytotoxicity." (PMID 39201585, 2024).
tumor (continued). "Furthermore, NETs skew the tumor microenvironment towards an immunosuppressive phenotype, e.g., by exhausting CD8+ cytotoxic T cells, the main effector cells of a PD-1/PD-L1 or CTLA4-directed immune checkpoint blockade." (PMID 39408949, 2024). "Tumor-infiltrating Tregs frequently exhibit a range of co-stimulatory molecules like CD27, ICOS, GITR, and OX40, along with co-inhibitory molecules such as CTLA-4, LAG-3, PD-1, and TIGIT." (PMID 38509593, 2024). "Depletion of CD4+ T cells, but not CD8+ T cells, prevented anti-CTLA-4 Ab-mediated anti-tumor effects, suggesting dependence on CD4+ T cells." (PMID 39106430, 2024). "In addition, tumor cDCs from patients with HCC were found to express inhibitory ligands such as PD-L1, Gal9 (ligand for TIM3), MHC-II (LAG3), CD86 and CD80 (CTLA-4)." (PMID 39146202, 2024). "They show anti-tumor activity against various targets such as EGFR, vascular endothelial growth factor (VEGF), PD-1, CTLA-4, receptor activator of nuclear factor-kappa B ligand (RANKL), insulin-like growth factor 1 receptor (IGF-1R), human epidermal growth factor receptor (HER2), cMET, and AXL." (PMID 38927911, 2024). "An animal model consisting of tumor-bearing Msh2loxP/loxP;TgTg (Vil1-cre) mice treated with an anti-PD-1 and anti-LAG-3 combination showed reduced circulating Tregs and lower levels of Tex cells positive for CTLA-4, LAG-3, and PD-1." (PMID 39273452, 2024). "Triple-therapy (DR-18 + anti–PD-1 + anti–CTLA-4) did not further inhibit tumor growth or prolong survival compared with the doublet (DR-18 + anti–CTLA-4)." (PMID 39561007, 2024). "We showed that the anti-tumor effects of anti-CTLA-4 therapy were dependent on CD4+ T cells, but not CD8+ T cells in this model." (PMID 39106430, 2024). "FoxP3 is a key regulatory gene for the development of Tregs that inhibits the antitumor immune response by producing immunosuppressive molecules, such as IL-10, CTLA-4 and PD-1, and releasing vascular endothelial growth factor (VEGF) to stimulate tumor angiogenesis." (PMID 39534095, 2024). "When performed in conjunction with CTLA-4 blockade, Cryo improved survival in a TRAMP C2 mouse model of prostate cancer, also generating intratumoral and systemic expansion of CD8+ T cells against the SPAS-1 tumor-specific antigen." (PMID 38957315, 2024). "The anti-tumor effects of CD8+T cells could also be enhanced by blocking inhibitory immune checkpoints such as PD-1, PD-L1, CTLA4, and LAG3." (PMID 38853203, 2024). "The administration of anti-PDL1 and/or anti-CTLA4 did not achieve a significant tumor growth delay compared to the control." (PMID 39199612, 2024). "In vivo mouse experiments indicate that CTLA-4-dependent antibodies bind to Fc receptors rather than blocking the action of CTLA-4/B7, demonstrating the anti-tumor effect of CTLA-4 antibodies." (PMID 39650663, 2024). "Experiments have shown that anti-CTLA-4 therapy combined with Treg consumption is more effective in inducing anti-tumor response than blocking CTLA-4 alone, reducing tumor Infiltrating Treg may be an important factor in determining immunotherapy response." (PMID 39845973, 2024). "The safety profile of JS007 monotherapy in this trial was excellent and comparable to that of CTLA-4 antibodies previously reported, regardless of the enrollment of patients with heterogeneous tumor types and multiple prior lines of therapy." (PMID 39354625, 2024). "Consequently, SLR-LNPs inhibited tumor growthin an RIG-I-dependent manner in multiple poorly immunogenic solidtumor models and increased therapeutic responses to anti-PD-1 andanti-CTLA-4 ICIs." (PMID 38652829, 2024). "In particular, immunological memory generated by the combination of anti-CTLA4 and TU2218 in the CT26 model prevented the development of tumors after additional tumor cell transplantation, suggesting that the TU2218-based combination has therapeutic potential in immunotherapy." (PMID 39105882, 2024).
tumor (continued). "In this pathway, the tumor reduces (downregulates) the number of activating co-stimulatory receptors (CD28, CD40, OX40, CD137) or increases (upregulates) the number of inhibitory surface receptors (LAG-3, CTLA4, B7-H3, PD-1) in dendritic cells." (PMID 37614091, 2024). "CTLA-4 blockade further delayed tumor growth independent of MQ pretreatment for the tumor cells in the vaccine." (PMID 37891002, 2024). "In these cases anti-PD-1/CTLA-4 blockade might enhance CD28 signaling and thereby could support T cell activation by local antigen presentation, thus improving tumour immune surveillance." (PMID 38440738, 2024). "The preclinical study indicated that JS007 could effectively block the CTLA-4/CD80 immune inhibitory signaling pathway, promote T-cell activation and proliferation, thereby boost the immune response to eliminate tumor cells." (PMID 39354625, 2024). "Treatment with CIRT together with CTLA4 blockade, but not with PD-L1 blockade, protected the mice from tumor growth on both sides, distal tumor metastasis, and mortality." (PMID 38474078, 2024). "Conversely, passive immunotherapy employs exogenous agents, such as monoclonal antibodies (anti-CTLA4, anti-PD1, anti-PD-L1) or adoptive cell transfers (ACT) with genetically engineered chimeric antigen receptor (CAR) T or NK cells, to exert anti-tumor effects." (PMID 38987565, 2024). "Overall, two-fraction IR resulted in improved tumor control compared to single-fraction IR without anti-CTLA4, while two IR fractions did not result in further benefit in combination with anti-CTLA4 relative to the single fraction." (PMID 39199612, 2024). "The main ligands of CTLA-4 are CD80 and CD86, which are expressed on both APCs and tumor cells." (PMID 38791528, 2024). "In addition, compared with neighboring tissues, CTLA4+CD8+T, SPP1+ macrophages and MRC1(CD206)+ CCL18+ macrophages were also enriched in tumor tissues in the samples of colorectal cancer liver metastasis." (PMID 38279145, 2024). "(What caused this peculiar effect is not clear although it has been observed that PD-1 or CTLA-4 blockade can promote other effects including tumor vascular normalization." (PMID 38498459, 2024). "Mice that rejected Y1.7AI or Y1.7LI tumors upon neo VAX or anti-CTLA-4 were rechallenged in the absence of any additional treatment with the same tumor lines at least 60 days after rejection of primary tumors." (PMID 38187708, 2024). "Additionally, anti-PD1 combined with anti-HAVCR2, CTLA4, or TIGIT has been recently found to more effectively improve T-cell function, overcome resistance to anti-PD1 therapy, and eliminate tumour cells." (PMID 38297380, 2024). "Meanwhile, tumor infiltrating lymphocytes co-express PD-1 and CTLA-4 at much higher levels compared to normal tissues and peripheral blood cells, thus anti PD-1/CTLA4 bi-specific antibody with a preferential tumor tissue enrichment over normal tissue would contribute to enhanced efficacy and safety." (PMID 39469707, 2024). "Combinatory ABx had neither a significant effect on tumor growth of the irradiated tumor nor on tumor progression of the abscopal tumor after RIT with anti-CTLA4." (PMID 38500667, 2024). "Treatment with anti-CTLA4 antibody was able to abrogate metastasis with no detrimental effects on its ability to induce tumor regression in exposed mice." (PMID 39221247, 2024). "The prognostic impact of CTLA-4 on tumor epithelial cells is favorable, since 5-year OS is 29% in CTLA-4 positive vs 19% in CTLA-4 negative primary tumors." (PMID 38384472, 2024). "CTLA-4 is thought to be expressed only on T cells, CD80 and CD86 mainly localizing to cell membranes and rarely expressing in tumor interstitium, are expressed in activated B lymphocytes, activated T lymphocytes, macrophages, peripheral blood mononuclear cells, and DCs." (PMID 39120585, 2024). "While inhibiting LDH did improve responses to CTLA-4 blockade, we found that combining LDHi with αPD-1 did not lead to an enhanced delay of B16 tumor growth." (PMID 39225102, 2024).
tumor (continued). "After 12 days, neither combination of ADU-S100 plus anti–PD-1 and anti–CTLA-4 nor ADU-S100 plus anti–CTLA-4 treatments showed a significant difference in tumor volume compared with ADU-S100 alone or ADU-S100 plus anti–PD-1 treatments." (PMID 38502231, 2024). "Indeed, a key role for the hypoxia-inducible transcription factor 1 (HIF-1) in the induction of CTLA-4 and LAG-3 expression on tumor infiltrating CD8+ T cells, as well as of programmed cell death ligand-1 (PD-L1) on cancer cells has been demonstrated." (PMID 38175205, 2024). "Additionally, a compelling finding suggests that the triple blockade of CTLA4, PDL1, and TIM3 represents an effective strategy for inhibiting the progression and migration of tumor cells in OS." (PMID 39431237, 2024). "Besides PD-1, CTLA4, and LAG3, other immune checkpoint molecules like TIM3 and TIGIT have also been identified as potential tumor-agnostic targets for T-cell-mediated cancer immunotherapy." (PMID 38920700, 2024). "The MC38-luc tumor-bearing mice which were cured by the combination therapy of vvDD-IL-9 and anti-CTLA-4 antibody were re-challenged with a high dose of MC38 (1.0 × 106 per mouse) in the left flank and challenged with irrelevant tumor control B16 (5.0 × 105 per mouse) in the right flank." (PMID 38473379, 2024). "In addition, intratumor heterogeneity (ITH), tumor VHL status, CTLA4 methylation levels, age, chromosomal changes, etc., are also important factors for predicting PD1/PD-L1 efficacy." (PMID 39014460, 2024). "Anti-CTLA4 blockade with ipilimumab or tremelimumab has been proven effective as immunotherapy in a diverse group of non-BC tumor types, but is not used in standard therapy for BC." (PMID 39478117, 2024). "CTLA4, a T-cell co-stimulatory molecule, primarily functions by binding with co-stimulatory molecules CD80/CD86, thereby inhibiting T-cell activity and weakening immune response, ultimately promoting tumor growth and metastasis." (PMID 38227081, 2024). "For example, anti-CTLA-4 antibodies are reported to enhance macrophage-induced ADCC of Tregs, promoting cancer clearance, whereas MAPKi can promote the secretion of TAM-derived angiogenic factors, supporting tumor growth." (PMID 38533720, 2024). "However, in addition to the expression of several immune checkpoints, including PD-1, PD-L1, and CTLA4, TIM-3, another inhibitory immune checkpoint expressed in T cells has been investigated to induce tumour infiltrating CD8 + T lymphocyte exhaustion in HCC." (PMID 38166741, 2024). "Similarly, the anti-CTLA-4 antibody blocks cytotoxic T-cell antigen 4 (CTLA-4) on the T-cells, prevents it from binding to its ligand B7 on the tumor cells, and therefore, turns off the inhibition of T-cell activity." (PMID 39061147, 2024). "Mice that rejected Y1.7AI or Y1.7LI tumors upon neoAg SLP vax or anti-CTLA-4 were rechallenged in the absence of additional treatment with the same tumor lines 60+ days after rejection of the primary tumors." (PMID 39446585, 2024). "Notably, in pre-clinical models, T-VEC was synergistic with anti-CTLA-4 (cytotoxic T-lymphocyte antigen 4) ICB therapy, resulting in an increase in tumor-specific CD3+ and CD8+ T cells." (PMID 38391959, 2024). "CTLA-4 plays a crucial role in maintaining normal immune balance, but tumor cells exploit its negative immune regulation to inhibit T cell activation." (PMID 38294629, 2024). "In the process of developing this regimen, we had previously shown that adding IT-IC and anti-CTLA-4 mAb to 12 Gy of RT did not significantly slow tumor growth, or prolong survival, over the 12 Gy of RT alone." (PMID 38731089, 2024). "Similarly, myeloid-derived suppressor cells (MDSCs) and T regulatory cells within the HNSCC tumor microenvironment (TME) express PD-L1 and the immunosuppressive molecule cytotoxic T lymphocyte antigen 4 (CTLA-4), respectively." (PMID 39435199, 2024).